ENSG00000281010
Gene: Small nucleolar RNA gene on chromosome 16 (2,155,025 to 2,155,104, reverse strand). Ensembl gene ENSG00000281010.
Gene Ontology:
Biological process: RNA processing
Cellular component: nucleolus